IGF1R (insulin like growth factor 1 receptor)
Diseases named in the same sentence as IGF1R in open-access papers (continued):
Sharing a sentence is not in itself a finding about the gene and the disease.
prostate tumors (16 papers, 2008 to 2023). "Inhibition of IGF‐1R using a human monoclonal antibody successfully inhibited both androgen‐independent and ‐dependent prostate tumour growth in vivo." (PMID 36569495, 2023). "Positive staining for phosphorylated IGF1R only appeared in prostate tumor epithelial cells of untreated samples." (PMID 36323713, 2022). "Increased Ki67+ staining also appeared in prostatic basal epithelium in HiMyc versus HiMyc-ARKO samples, indicating the promotional role of IGF1R activation in prostatic tumor epithelia (p = 5.66 × 10−5)." (PMID 36323713, 2022). "Collectively, these results suggest upregulation of IGF1R mediates residual PI3K activity and promotes resistance to p110α + p110β dual inhibition in PTEN-deficient prostate tumors." (PMID 34417459, 2021). "One in vivo study demonstrated that β1-integrins produced inhibitory signals in an insulin-like growth factor 1 receptor-dependent manner in irradiated prostate tumors." (PMID 30828330, 2019). "To confirm the clinical relevance of our experimental observations, we examined the gene expression levels of IGF-1R by qRT-PCR in a retrospective cohort of 270 primary prostate tumors." (PMID 25906745, 2015). "And notably, an increased ratio of INSR/IGF1R expression has recently been described in prostate tumours and adjacent tissue, which suggests specifically that insulin signalling plays a key role in these tumours." (PMID 23573093, 2013). "A better understanding of the molecular determinants of aberrant IGF-1R expression in prostate tumors is thus required to define subgroups of patients who may benefit from anti-IGF-1R therapies." (PMID 25906745, 2015). "Proteins such as c-Src tyrosine kinase, IGF-R (insulin-like growth factor 1 receptor) and FAK (focal adhesion kinase) all play imperative roles in the formation and advancement of prostate tumors." (PMID 37842237, 2023). "In addition, many tumour types, including prostate tumours, upregulate the expression of related insulin receptor (INSR), IGF-1 receptor (IGF-1R), and hybrid INSR/IGF-1Rs further promoting insulin-driven cancer survival pathways." (PMID 23573093, 2013). "As a cell transforms to a malignant state, MEIS1/2 are epigenetically silenced in more aggressive prostate tumors and expression of tumor-suppressive proteoglycans is suppressed, leading to decreased regulation of oncogenic signaling through pathways such as TGFβ, EGFR, cMYC, WNT, and IGF1R." (PMID 32553107, 2020).
head and neck squamous cell carcinoma (15 papers, 2011 to 2025). A squamous cell carcinoma that arises from any of the following anatomic sites: lip and oral cavity, nasal cavity, paranasal sinuses, pharynx, larynx, and salivary glands. "Downregulation of the expression of HIF‐1α led to an increase in the sensitivity of head and neck squamous cell carcinoma to the OSI-906 IGF1R small molecule inhibitor by a mechanism involving the increase in apoptosis." (PMID 35307810, 2022). "A study in head and neck squamous cell carcinoma has experimentally validated the interaction between IGF1R and let-7c-5p, connecting silenced expression of IGF1R to decreased proliferation, migration, and epithelial-mesenchymal transition (EMT)." (PMID 36289686, 2022). "It is also of note that AC-480 exhibited increased cell line-dependent synergistic or additive apoptosis in head and neck squamous cell carcinomas when used as a co-inhibitor with the insulin-like growth factor-1 receptor 1 (IGF1R) inhibitor, BMS-754807." (PMID 25251190, 2014). "Chen at al. obtained similar results and observed down-regulation of both mTOR and IGF1R after transfection with miR-99 family members in head and neck squamous cell carcinoma." (PMID 22920721, 2012). "Patients diagnosed with head and neck squamous cell carcinoma (HNSCC) and having a high IGF-1R expression level had a significantly shortened overall survival." (PMID 40282476, 2025). "We investigated the effects of cetuximab (EGFR antibody) and IMC-A12 (IGF-1R antibody) on the response of head and neck squamous cell carcinoma (HNSCC) to radiation therapy (RT)." (PMID 25355701, 2015). "Epidermal growth factor receptor (EGFR) inhibitors have limited efficacy in head and neck squamous cell carcinoma (HNSCC) due to various resistance mechanisms, such as activation of the insulin-like growth factor-1 receptor (IGF1R), which initiates pro-survival signaling." (PMID 30729097, 2019). "This review highlights three RTK signaling pathways involved in head and neck squamous cell carcinoma; EGFR, the type 1 insulin-like growth factor receptor (IGF-1R) and the hepatocyte growth factor (HGF) receptor (Met)." (PMID 21776391, 2011).
soft tissue sarcoma (15 papers, 2011 to 2025). A malignant neoplasm arising from muscle tissue, adipose tissue, blood vessels, fibrous tissue, or other supportive tissues excluding the bones. "Increased MDM2 expression can cause downregulation of IGF-1R and in some cancers, such as soft tissue sarcoma, MDM2 expression is associated with a more malignant phenotype." (PMID 24489919, 2014). "Preclinical evidence suggests that IGF-1R signaling is likely to be vital for soft-tissue sarcomas as well." (PMID 24212944, 2011). "The ORR with apatinib was 70% for ES, 40.9% for osteosarcoma, 100% for chondrosarcoma, and 71.4% for soft tissue sarcoma, indicating that combination therapy with IGF-1R may be therapeutically more efficient for cancer patients." (PMID 32754598, 2020). "BKM120 in combination with IGF1R inhibitor AEW541 and mTOR inhibitor rapamycin have been evaluated in pediatric bone and soft tissue sarcomas." (PMID 28662162, 2017). "Notably, TEM1, VEGFR-1, EGFR, VEGFR-2, IGF-1R, PDGFRα, and CD40 are highly expressed in the tumor cells of soft tissue sarcoma." (PMID 40258773, 2025). "The promoter activity of IGF-1R is significantly activated by the binding of EWS-WT1 with the -331 to -40 region of the IGF-1R promoter in desmoplastic small round cell tumor (DSRCT), a malignant soft tissue sarcoma occurring in young children." (PMID 32754598, 2020). "The most obvious biomarker would be expression of the IGF-1R, but a Phase 2 trial with Cixutumumab (IGF-1R antibody) and Temsirolimus (mTOR inhibitor) in patients with bone and soft-tissue sarcomas showed that IGF-1R expression does not correlate with therapeutic response." (PMID 26563243, 2016).
asthma (14 papers, 2016 to 2025). "For this purpose, Igf1r deficiency was preventively or therapeutically induced in mice to evaluate the implication of Igf1r in acute asthma pathobiology and resolution of airway inflammation following HDM exposure." (PMID 29272313, 2017). "Thus, Igf1r deficiency was preventively-induced to study the implication of Igf1r in acute asthma pathobiology." (PMID 29272313, 2017). "In obese asthma patients, we found higher hsa-miR-26a-1-3p and IGF-1R values and lower values for hsa-miR-376a-3p and IGFBP-3." (PMID 37511378, 2023). "miR-133a plays an important role in asthma airway remodeling by targeting IGF1R and regulating α-SMA expression." (PMID 36611831, 2022). "miR-133a plays a key role in asthma airway remodeling by targeting IGF1R through the PI3K/AKT/mTOR signaling pathway to regulate α-SMA expression." (PMID 36611831, 2022). "Downregulation of miR-133a contributed to upregulation of RhoA in bronchial smooth muscle cells of asthmatic patients and alleviates airway remodeling in asthma by targeting IGF1R." (PMID 36172292, 2022). "We aimed to determine if therapeutic targeting of IGF1R ameliorates established allergic airway inflammation in a murine model of HDM-induced asthma." (PMID 34440118, 2021). "Here, we aimed to determine if therapeutic targeting of IGF1R ameliorates allergic airway inflammation in a murine model of asthma." (PMID 34440118, 2021). "We aimed to determine if therapeutic targeting of IGF1R ameliorates allergic airway inflammation in a murine model of asthma." (PMID 34440118, 2021). "IGF-1R deletion reduces the infiltration of immune cells as well as the expression of inflammation markers in the lung tissues in a murine model of asthma." (PMID 33511137, 2020). "Platelets play a significant role in asthma through miR-223-induced, advanced glycation end product-mediated vascular endothelial cell apoptosis via decreasing IGF-1R." (PMID 30018981, 2018). "Regarding increased Igfbp3 and Igfbp5 levels in HDM-treated Igf1r-deficient mice, exogenous IGFBP3 and IGFBP5 administration blocks the physiological consequences of asthma and enhances epithelial cell adhesion to maintain the epithelial-mesenchymal boundary." (PMID 29272313, 2017). "Our results demonstrate for the first time that Igf1r is important in acute asthma pathobiology and resolution of HDM-induced inflammation." (PMID 29272313, 2017). "We assert that IGF1R is suggested to be a promising candidate for future therapeutic approaches for the treatment and prevention of asthma." (PMID 29272313, 2017). "Interestingly, in obese asthma patients, elevated levels of miR-26a-1-3p and IGF-1R were observed, while miR-376a-3p and IGFBP-3 levels were decreased." (PMID 41156032, 2025). "Therefore, we deemed that our asthma model was appropriate for testing the in vivo anti-asthmatic efficacy of IGF1R inhibition using the IGF1R TKI inhibitor NVP-ADW742 (NVP)." (PMID 34440118, 2021). "A recent study demonstrated that miR-223 affects the PI3K/Akt signaling pathway by targeting IGF-1R and may become a promising target for the future treatment of asthma and airway remodeling." (PMID 32631807, 2021). "A recent study discloses novel roles of IGF-1/IGF-1R signaling in asthma." (PMID 30018981, 2018). "Notably, neutrophil and eosinophil presence in BALF and asthma-related features were counteracted in a similar manner in HDM-treated mice following therapeutic targeting of Igf1r." (PMID 29272313, 2017). "Notably, we have recently reported that IGF1R plays an important role in initiation of the inflammatory response in mice, and the importance of IGF1R in the pathogenesis of murine asthma, mediating both AHR and mucus secretion after chronic HDM exposure." (PMID 29272313, 2017). "From these data we can conclude that both Igf1r and Igf1 may be important mediators in the establishment of murine asthma, and that Igfpb3 and Igfpb5 could play protective roles against HDM-induced allergic inflammation." (PMID 29272313, 2017).
asthma (continued). "Thus, IGF1R is suggested to be a promising candidate for future therapeutic approaches for the treatment and prevention of asthma." (PMID 29272313, 2017). "In addition, IGF1R could be considered a promising candidate biomarker in asthma." (PMID 34440118, 2021). "Our results demonstrate that the pharmacological blockade of IGF1R with NVP-ADW742 ameliorates HDM-induced allergy, and places IGF1R as a potential pharmacological target for future therapeutic approaches in asthma." (PMID 34440118, 2021). "Being as the basis for asthma treatment, steroids appear to inactivate IGF-1/IGF-1R signaling indirectly or directly by downregulating the expression of IGF-1 and IGF-1R both locally and systemically." (PMID 30018981, 2018). "Although Insulin-like growth factor 1 receptor (IGF1R) was found to be involved in asthma, its pharmacological inhibition has not previously been investigated in this pathology." (PMID 34440118, 2021). "HDM-mediated induction of Igf1 could be responsible for IGF1R phosphorylation to promote the asthmatic response, and therefore supports why targeting IGF1R with NVP ameliorates HDM-induced asthma." (PMID 34440118, 2021). "Anti-IGF1R and anti-TSLP are IgG monoclonal antibodies (mAbs) directed against human Insulin-like Growth Factor 1 Receptor for anti-tumor activity and Thymic Stromal Lymphopoietin cytokine for anti-asthma activity, respectively." (PMID 32656609, 2020). "Migration of airway epithelial cells could be stimulated by IL-4, possibly via IRS-1/IRS-2 signaling independent of IGF-1/IGF-1R in an asthma model." (PMID 30018981, 2018). "However, the IGF1R inhibitor NVP has still not been investigated in asthma." (PMID 34440118, 2021). "Moreover, airway epithelial-specific depletion of Igf1r before, but not after, house dust mite exposure, renders mice more asthma-prone than control mice, as manifested by increased airway hyperresponsiveness, more extensive apoptosis and eosinophil, and CD4+ T cell infiltration in the lungs." (PMID 30018981, 2018).
esophageal squamous cell carcinoma (14 papers, 2012 to 2024). Esophageal squamous cell carcinoma (ESCC) is a type of esophageal carcinoma (EC) that can affect any part of the esophagus, but is usually located in the upper or middle third. "Studies suggest a strong correlation between the overexpression of IGF-1R and a poor prognosis in esophageal squamous cell carcinoma." (PMID 38413558, 2024). "The tumor suppressive effect of miR-365 in esophageal squamous cell carcinoma was demonstrated in vivo and in vitro by identifying IGF1R as a target of miR-365, an important component of the PI3K-AKT/PKB pathway." (PMID 34199293, 2021). "This study evaluated the antitumor efficacy of the EGFR/HER2 inhibitors, gefitinib and lapatinib, in combination with the IGF-1R inhibitor, linsitinib, on the esophageal squamous cell carcinoma (ESCC)." (PMID 36142299, 2022). "FOXC1, in turn, promotes esophageal squamous cell carcinoma stem-like properties by transactivating CBX7 and IGF-1R." (PMID 38413558, 2024). "The reduction of CAF-derived exosomal miR-100-5p in esophageal squamous cell carcinoma (ESCC) may promote the growth, migration, and invasion of tumor-related lymphatic endothelial cells by increasing the expression of IGF1R/PI3K/AKT, ultimately leading to the development of lymphatic vessels." (PMID 38694824, 2024).
renal carcinoma (14 papers, 2014 to 2022). A carcinoma arising from the epithelium of the renal parenchyma or the renal pelvis. "We previously uncovered that MTAP‐deficient renal carcinoma cells become addicted to IGF1R activity to drive oncogenic pathways, so the selective IGF1R inhibitor preferentially impairs their viability and invasiveness." (PMID 35766227, 2022). "According to genes encoding proteins related to insulin receptors, IGF1R is able to stimulate renal cancer cells." (PMID 32694937, 2020). "Study of nuclear IGF1R in primary renal cancer cells revealed that IGF1R expression was associated with poor prognosis in renal cancer." (PMID 27405474, 2016). "Work by Aleksic and colleagues showed that higher levels of nuclear IGF-1R were associated with poor prognosis in renal cancer, suggesting that nuclear IGF-1R contributes to an aggressive phenotype." (PMID 26217584, 2015). "Finally nuclear IGF-1R was detected in primary renal cancer tissues of high proliferation rate and was associated with adverse prognosis." (PMID 27405474, 2016). "The team found that a selective IGF1R inhibitor, called linsitinib, suppressed colony-forming ability and reduced cell motility in renal carcinoma cells." (PMID 30701095, 2019). "Owing to the sequence complementarity of IGF1R transcript containing a long 5’UTR-binding sites with HuR, we speculated that exosomal miR-155-5p may affect IGF1R expression by regulating HuR-dependent IGF1R mRNA stability in renal cancer." (PMID 34131104, 2021). "Moreover, nuclear IGF1R staining correlated with an adverse prognosis in renal cancer." (PMID 36479090, 2022). "Taken together, transfer of miR-155-5p from hypoxic TAMs by exosomes to renal cancer cells explains the oncogenic manner, in which M2 macrophages confer the malignant phenotype to RCC cells by enhancing HuR-mediated mRNA stability of IGF1R." (PMID 34131104, 2021). "Aleksic and colleagues reported that nuclear IGF1R was present in renal cancer cells, preinvasive breast lesions and non-malignant tissues with a high proliferative index." (PMID 36479090, 2022). "The findings suggest that IGF1R signaling drives pathways that contribute to the aggressive nature of renal carcinoma cells lacking MTAP." (PMID 30701095, 2019). "Thus, the most likely mechanism for the resistance of VHL-defective renal cancer cells to 2DG-ABT therapy is that in the absence of VHL, IGF1R expression is stabilized, thus activating AKT." (PMID 27460078, 2016).
autoimmune disease (13 papers, 2014 to 2025). A disorder resulting from loss of function or tissue destruction of an organ or multiple organs, arising from humoral or cellular immune responses of the individual to their own tissue constituents. "IGF-1R signaling influences the activation and trafficking of immune cells, indicating a broader role in fibroblast dysregulation associated with autoimmune diseases." (PMID 40718626, 2025). "The identified targets TGFBR1 and IGF1R have been shown to be downregulated in blood cells of patients with autoimmune disease and a loss of SP1 and knockdown of GNAI1 have been described to impair hematopoiesis and immune cell migration capability, respectively." (PMID 31569706, 2019). "Another study showed that IgG antibodies from GD patients and from RA patients can induce cytokines (including IL-16) not only in their own fibroblasts but in the fibroblasts of patients with other autoimmune disease through the insulin-like growth factor-1 receptor (IGF-1R)." (PMID 38340224, 2024). "At present, it is unknown how inhibition of IGF-1R by linsitinib mediates upregulation of arginase-1 in the context of an autoimmune disorder in the bone marrow." (PMID 37810891, 2023). "Our data indicate that IGF-1R could be a potential target for new therapies for the treatment of autoimmune diseases where autoreactive T cell expansion is a requisite for disease." (PMID 24718491, 2014). "The oral IGF-1R inhibitor linsitinib blocks the development of the local pathologies of GD and TED in an early and late phase of the autoimmune disorder and also prevents development of the autoimmune response." (PMID 37435490, 2023). "As an autoimmune disease, TAO is characterized by sensitive T cells and antibodies against autoantigens, such as thyrotropin receptor (TSHR) and insulin-like growth factor-1 receptor (IGF-1R)." (PMID 37176063, 2023). "Our research reveals the potent therapeutic effect of costunolide in AIH and the potential role of SRC and IGF1R in AIH for the first time, which may further contribute to the novel drug development for AIH and other autoimmune diseases." (PMID 37163367, 2023).